TRIB3 (tribbles pseudokinase 3)
Diseases named in the same sentence as TRIB3 in open-access papers (continued):
Sharing a sentence is not in itself a finding about the gene and the disease.
tumor (continued). "Tribbles pseudokinase 3 (TRIB3), a member of the mammalian pseudokinase tribbles family, is involved in multiple biological processes, including tumor progression." (PMID 37025600, 2023). "In colon cancer, TRIB3 reduces immune infiltration of CD8+ T cells by inhibiting the STAT1-CXCL10 pathway, thereby mediating tumor cell immune evasion." (PMID 38235126, 2023). "More importantly, we further demonstrated that TRIB3 interacted with AKT1 to up-regulate FOXO1 and SOX2 expression, which was indispensable for the pro-tumor effects induced by integrin αvβ3." (PMID 35473511, 2022). "Thus, it is suggested that TRIB3 may be a safe and effective novel target for tumor therapy." (PMID 35726370, 2022). "We demonstrated that the pro-tumor effects and the activation of SOX2 was dependent on a TRIB3 manner, and the patient prognosis was influence by the TRIB3 expression." (PMID 35473511, 2022). "Thus, TRIB3 expression could be detected in both the nucleus and the cytoplasm of tumor cells." (PMID 34771470, 2021). "These stress-proteins can regulate (inhibit) tumor generation and production alongside other transcriptional factors such as endoplasmic reticulum-ATF4, TRIB3, and CHOP, and enhance autophagy." (PMID 32839414, 2020). "PCM4 inhibited the tumor growth of PDXs (T64, T69, T144, T123, T174, T169, and T156) with high TRIB3 and MYC expression compared with PDXs (T151, T1, and T3) with low TRIB3 and MYC expression." (PMID 33298911, 2020). "Tribbles pseudokinase 3 (TRIB3) is a scaffolding protein that regulates intracellular signal transduction, and its role in tumor development is controversial." (PMID 33334065, 2020). "Tribbles pseudokinase 3 (TRIB3) protein is a pseudokinase which plays an important role in cellular stress, metabolism, and tumor progression." (PMID 32874132, 2020). "A recent study identified that TRIB3 was up-regulated in NSCLC that promoted the metastasis and tumor growth." (PMID 29367413, 2018). "Moreover, TRIB3 has been found to interact with STAT3, mediating angiogenesis and promoting tumor metastasis." (PMID 39881875, 2024). "This phenomenon suggests that the highly expressed TRIB3 and NQO1 in blood-derived exosomes may originate from this particular subpopulation of highly stem-like HCC tumor cells." (PMID 39044829, 2024). "Furthermore, our data showed that the key genes, TRIB3 and NQO1, were not only correlated with the survival outcome and clinical stage of HCC but were also highly expressed within a subpopulation of tumor cells characterized by enhanced stemness." (PMID 39044829, 2024). "The finding that TRIB3 is highly expressed in RCC has been confirmed in several studies, and the elevated TRIB3 expression in RCC patients is correlated with clinicopathologic features (e.g., tumor grade and stage) of the tumor and prognosis." (PMID 38006403, 2023). "Moreover, the TRIB3 location in tumor tissues and subcellular structures was identified via Tisch in the HPA database, and the potential protein interaction molecules for TRIB3 were elucidated in the STRING database." (PMID 38235126, 2023). "TRIB3 and FABP1 may interact with CEACAM5, PRAP1, GABRP and THBS4, and affect tumor immune microenvironment by regulating immune cells, and participate in the development and progression of GC." (PMID 34957220, 2021). "Bioinformatics analysis showed that TRIB3 and FABP1 may interact with CEACAM5, PRAP1, GABRP, and THBS4, and affect tumor immune microenvironment by regulating immune cells, and participate in the development and progression of GC." (PMID 34957220, 2021). "IHC results showed that the CAV1, AKR1C3, and TRIB3 protein expression levels were significantly higher in HNSCC tumor tissues (P < 0.05), but the difference in AURKA was not significant (P = 0.144)." (PMID 34539737, 2021). "The expression of TRIB3 protein was positively correlated with its mRNA expression, though not all of the analyzed cases showed higher TRIB3 levels in tumor regions than in normal regions." (PMID 34198908, 2021).
tumor (continued). "Knocking down of TRIB3 inhibited tumor growth, metastasis, and increased the survival rate of tumor-bearing mice in NSCLC PDX and A549 xenograft models, confirming the tumor-promotion role of TRIB3 in NSCLC." (PMID 32694521, 2020). "Bioinformatic analyses of public databases combining mRNA/protein expression of TRIB3 are upregulated in GBM patient samples and increase the poor prognosis of GBM patients, suggesting that TRIB3 may function as a tumor promoter and may have therapeutic value." (PMID 33203798, 2020). "Importantly, interrupting the TRIB3/AKT1 interaction by a modified α-helix peptide, Pep2–Ae, accelerated FOXO1 degradation, reduced SOX2 accumulation, and decreased the tumor-initiating capacity in MMTV-PyMT and PDX mice." (PMID 31844113, 2019). "Among these four genes, we determined that SOX7-activated SPRY1 and SLIT2, and SOX7-repressed TRIB3 and MTHFD2 could all differentially contribute to SOX7-mediated tumor suppression." (PMID 29757932, 2018). "This suggests that TRIB3 marks or supports tumor aggressiveness rather than reflecting hypoxia itself." (PMID 21864376, 2011). "But TRIB3 had no close relationship with immune cells through correlation with tumor purity." (PMID 37626099, 2023). "Moreover, some of the candidate genes, such as TRIB3, KRT80, and FAM135B, were found to be correlated with tumor stage or survival outcomes, implying that these candidate genes could serve as promising prognostic biomarkers for COAD patients." (PMID 35610288, 2022). "However, metastatic sites, tumor size, invasion, lymph node metastasis or lymphatic and venous invasion, were not significantly correlated with TRIB3 levels." (PMID 34198908, 2021). "Moreover, immunofluorescence and immunoblotting on the final day of treatment showed that the levels of TRIB3, LC3II and cleaved C3 were enhanced in these tumours when they had been treated with GA, supporting the idea that this compound also induces autophagy-mediated cell death in vivo." (PMID 31578236, 2019). "Since TRIB3 expression is related to T-stage and TNM is closely related to tumor stage and grading, TNM was not included as a variable in the univariate Cox regression analysis to reduce collinearity between variables." (PMID 38235126, 2023). "SAH-JGZ4 administration inhibited tumor growth of NCI-H460 cells but not NCI-H157 and NCI-H2170 cells, suggesting that tumors with high expression of both TRIB3 and EGFR would be sensitive to SAH-JGZ4 treatment." (PMID 32694521, 2020). "Notably, TRIB3 overexpression did not alter the expression profile of angiogenesis‐related genes in vitro, suggesting that TRIB3 may exert its effects indirectly, potentially through modulation of the tumor microenvironments, to promote tumor growth, angiogenesis, and metastasis." (PMID 39932456, 2025). "The data suggest that TRIB3 is induced by hypoxia in an ATF4 dependent manner and supports hypoxia sensitivity, but from the measurements of other hypoxia markers we find that TRIB3 mRNA abundance from tumor biopsies is not merely a reflection of tumor hypoxia." (PMID 21864376, 2011).
cardiovascular disease (7 papers, 2013 to 2024). "Nevertheless, we consider our findings important in attempting to understand the pathophysiological interaction between the TRIB3 Q84R polymorphism and cardiovascular disease." (PMID 34051802, 2021). "Together these results suggest TRIB3 upregulates macrophage matrix production and reduces MMP expression, resulting in weakened fibrous caps and potentially increased plaque instability associated with acute cardiovascular disease events." (PMID 36158793, 2022). "Among these, 10 regions, proximal to or within the genes OVAAL, BMP3, RIOK1, AC096553.5, MCPH1, KCNU1, GLIS3, TUT7, TRIB3, and SYNDIG1, represent novel associations with MI and have not been previously linked to Cardiovascular disease (CVD)-related traits." (PMID 38725839, 2024).
infection (7 papers, 2017 to 2025). The state of being infected such as from the introduction of a foreign agent such as serum, vaccine, antigenic substance or organism. "Both CHOP and TRIB3 showed robust induction in macrophages after infection with lytic Hc strains, and this correlated with protein levels." (PMID 28953979, 2017). "Two pro-apoptotic components of ISR signaling, the transcription factor CHOP and the pseudokinase TRIB3, are necessary for robust macrophage death during in vitro infection." (PMID 28953979, 2017). "Both CHOP-/- and TRIB3-/- macrophages showed a reduction in caspase-3/7 activity after infection with wildtype Hc." (PMID 28953979, 2017). "Based on these studies, we speculate that the infection of Hp may regulate TRIB3 expression through the ubiquitination-proteasome pathway mediated degradation." (PMID 34957220, 2021). "Cells with the largest intracellular DENV abundance show little change in the expression of apoptosis effector genes such as caspases, while their upstream regulators such as DDIT3 and TRIB3 are clearly overexpressed during late infection, in line with a prior report (Peña and Harris, 2011)." (PMID 29451494, 2018). "Here we demonstrate that Hc strains expressing lytic CBP1 alleles trigger the integrated stress response (ISR) in macrophages during infection, leading to an induction of the pro-apoptotic genes CHOP and Tribbles 3 (TRIB3)." (PMID 28953979, 2017). "Furthermore, robust TRIB3 expression after infection with Hc secreting wildtype Cbp1 is dependent on CHOP, as CHOP-/- macrophages showed reduced TRIB3 induction after infection with wildtype Hc or the complemented cbp1 mutant strain." (PMID 28953979, 2017).
neurodegenerative disease (2 papers, 2017 to 2021). A disorder of the central nervous system characterized by gradual and progressive loss of neural tissue and neurologic function. "The relatively mild cognitive and memory brain phenotypes observed in a C57BL/6 TRIB3-deficient mouse model support the notion that normalizing pathological increases in TRIB3 levels in neurodegenerative disease might be an interesting new medical strategy." (PMID 27908682, 2017).
blood cancer (1 paper, 2020). "Notably, TRIB3 knockdown decreases MYC expression in most blood cancer cells but not in U937 AML cells or bjab BL cells." (PMID 33298911, 2020).
cardiac disease (1 paper, 2020). "TRIB3 has not been linked to any cardiac disease; however, the amino acid is highly conserved among distant species." (PMID 32013205, 2020).
vascular disorder (1 paper, 2022). A general term used to describe any disease affecting blood vessels]. "For example, TRIB3 is involved in the regulation of switching phenotypes in vascular smooth muscle cells and thus has an impact on vascular disorders." (PMID 36105108, 2022).
TRIB3 also shares sentences with these, for which no sentence is quoted: metabolic disease (6 papers); Alzheimer disease (3); chronic kidney disease (2); Hypertension (2); metastatic disease (2); pulmonary hypertension (2); acne (1); alveolar rhabdomyosarcoma (1); amyotrophic lateral sclerosis (1); dementia (1); dilated cardiomyopathy (1); ER Stress (1); essential hypertension (1); fibrosarcoma (1); gastric adenocarcinoma (1); Glucose intolerance (1); head and neck tumors (1); heart failure (1); Hepatitis (1); hyperlipidemia (1); IgA nephropathy (1); ischemic stroke (1); kidney (1); laryngeal squamous cell carcinoma (1); multiple sclerosis (1); myeloid leukemia (1); myocardial infarction (1); oral cancer (1); oropharyngeal carcinoma (1); overnutrition (1).
A further 10 diseases each share a sentence with TRIB3 in 1 paper.